EPAS1 (endothelial PAS domain protein 1)
Diseases named in the same sentence as EPAS1 in open-access papers (continued):
Sharing a sentence is not in itself a finding about the gene and the disease.
tumor (continued). "In fact, PPGL, together with ccRCC, are the tumor types with the highest levels of EPAS1 mRNA." (PMID 35740651, 2022). "It is important to note that there are studies that report EPAS1/HIF-2α as a tumor suppressor." (PMID 35267567, 2022). "Mutations in the EPAS1 sequence were statistically correlated with the absence of cancer perforation, high tumour grade and pathological stage of patients with CRC." (PMID 34250767, 2021). "However, DNMT3A was found to methylate and inactivate the HIF-2α gene EPAS1, and inactivation of DNMT3A in the early stages of tumor cell progression leads to abnormal activation of EPAS1." (PMID 33109235, 2020). "Analyzing the methylation of the EPAS1 target region in circulating tumor cells (CTCs) could prove insightful." (PMID 33218035, 2020). "In addition, the association of molecular dysregulation in DNA number, mRNA expression, and mutations in ESCC along the clinical significance of the gene has provided critical insights of tumor-promoting properties of EPAS1 in the pathogenesis of ESCC." (PMID 33042797, 2020). "However, some other studies reported tumor inhibitory functionality of EPAS1 in various cancer models." (PMID 33042797, 2020). "On the contrary, in EPAS1 mutation-negative tumour tissues (n = 8), 75% of samples showed no change or low expression and 25% of patients had shown high EPAS1 protein expression." (PMID 33114456, 2020). "Additionally, while it did not pass our multiple testing significance threshold, we also observed a candidate association between the EPAS1 germline variant rs57579899 and SETD2 tumor mutation (p = 0.012)." (PMID 33121461, 2020). "So even though inhibition of hypoxia-responsive EPAS1 results in the loss of stemness, inhibition of tumor growth, and favorable outcome, such strategy is not cancer cell-specific." (PMID 32413951, 2020). "Thus, the gain-of-function mutations of EPAS1 can lead to increased expression of VEGF and Flt1 in endothelial cells, which in turn promotes angiogenesis, thereby promoting tumour growth and progression." (PMID 33114456, 2020). "We introduce floxed alleles of Hif1a and Hif2a (also known as Epas1) into this genetic background and show that HIF-1α is essential for tumour formation whereas deletion of HIF-2α has only moderate effects on tumour onset and growth rate but leads to increased intra-tumoural immune activation." (PMID 32807776, 2020). "EPAS1 DNA number changes correlated with the location of tumour in patients." (PMID 33114456, 2020). "Surprisingly, hypoxia-inducible factors were not among the nominated high confidence SDH-loss MRs, although HIF2α (encoded by EPAS1) was nominated as a MR for VHL-loss tumors, controlling ~ 5% of the observed differentially-expressed genes in that tumor subtype." (PMID 31234811, 2019). "Of the three isoforms, HIF-1 is frequently overexpressed in tumor cells, with HIF-2 [endothelial PAS domain protein 1 (EPAS1)] strongly expressed by subsets of tumor-associated macrophages and HIF-3 expressed in pulmonary alveolar epithelial cells and in human kidney." (PMID 30761299, 2019). "Additionally, ADR treatment showed weakly inhibitory effects on the tumor volumes and tumor weights in sh‐NC xenografted mice (P < 0.05), and tumor growth was notably decreased in sh‐EPAS1 xenografted mice treated with ADR (P < 0.001)." (PMID 30536571, 2019). "Notably, EPAS1 was nominated as the top-ranking SDHC-loss MR gene, in contrast to the SDH-loss human PPGL tumor analysis." (PMID 31234811, 2019). "FOXF1 and EPAS1 are TFs that have been demonstrated to participate in tumor progression." (PMID 31106044, 2019). "According to recent studies, the high level of EPAS1 expression could lead to a poor prognosis by increasing the tumor size and angiogenesis." (PMID 29636077, 2018). "Initially, we analysed Epas1 expression over time in the KP tumour model." (PMID 26837714, 2016). "PCR analysis confirmed efficient Epas1 deletion in KPH2 tumours." (PMID 26837714, 2016).
tumor (continued). "Consistent with this hypothesis, tumours from UPS-bearing mice treated with SAHA for only 4 days displayed significantly increased Epas1 mRNA levels." (PMID 26837714, 2016). "We speculated that HIF1A and EPAS1 overexpression in patients with high-risk NBL will contribute to differentiation therapy resistance and to tumor cell aggressiveness." (PMID 26057707, 2015). "EPAS1 has also been reported to repress miR-15–16, leading to tumor angiogenesis and metastasis." (PMID 26587830, 2015). "Functional assays have shown that these mutations lead to stabilization of HIF1α, causing overexpression of hypoxia-induced angiogenic pathway genes, such as VEGF (vascular endothelial growth factor) and EPAS1 (endothelial PAS domain protein 1), providing therefore support for tumor growth." (PMID 24899893, 2014). "As EPAS-1 plays an important role in tumor cell survival and proliferation via participating indispensably in SP-1 transcription factor-mediated FBI-1 induction, it could be a novel therapeutical target for cancer intervention." (PMID 25192290, 2014). "However, clinical correlations and experimental investigations have indicated similarities of EPAS1 lesions to SDHx and VHL mutated tumours." (PMID 24466223, 2014). "Furthermore, somatic mutations in genes like EPAS1 (encoding HIF-2α) and ATRX have been implicated in tumor development and aggressiveness, broadening the genetic landscape of PPGLs and highlighting the heterogeneity even within tumor subtypes." (PMID 41597272, 2026). "However, it was shown that comparing HIF1A to EPAS1 proteins, despite their primary role as transcription factors for cellular response to hypoxia, could play independent or/and coregulatory roles in tumor physiology and progression." (PMID 39888575, 2026). "Finally, we tested whether expression of exogenous Epas1 enhances anti-tumor activity of aged CD8 TCR-T cells as reported in young CD8 T cells." (PMID 39925817, 2025). "However, in thyroid malignancies, EPAS1 acts as a tumor suppressor." (PMID 40308576, 2025). "Moreover, retroviral expression of Epas1 improves anti-tumor responses of aged CD8 T cells in ACT." (PMID 39925817, 2025). "Thus, Epas1 may be a biomarker to predict the age-related decline in anti-tumor efficacy of ACT using tumor-specific CD8 T cells." (PMID 39925817, 2025). "The expression levels of Epas1 and Vegf mRNA in the tumor tissue of the TH mice were lower in comparison with the control group, while the levels of Hif1a, Epas1, and Hif3a mRNA expression in the peritumoral area were statistically significantly higher relative to the tumor tissue." (PMID 39063041, 2024). "RCC tumor xenografts developed resistance to PT2399 when treated for over 100 days, which may be mediated by a G323E mutation in EPAS1 (endothelial PAS domain-containing protein 1) encoding for HIF-2α." (PMID 38339352, 2024). "In addition, EPAS1, after nuclear translocation, may activate genes involved in tumor angiogenesis, invasion, and metastasis." (PMID 37447165, 2023). "Furthermore, residual tumor, metastasis status, margin status, EPAS1 expression might be independent prognostic factors for OS in STS patients." (PMID 34982796, 2022). "However, this association is not absolute, as low EPAS1 protein expression was in some cases associated with advanced tumor stage." (PMID 34828399, 2021). "The fact that vCAFs are enriched in the tumor core may indicate that hypoxia is fueling the detachment of vCAFs from its perivascular niche; a notion that is further supported by their expression of Epas1 (HIF2-α)." (PMID 30514914, 2018). "HIF2A, also known as endothelial PAS domain protein 1 (EPAS1), was also described as a factor related to tumor progression." (PMID 39888575, 2026). "On day 12 after the adoptive transfer of OT-I T cells with Epas1-Crispr or control-Crispr into young recipient mice with B16-OVA tumors, we collected tumor-infiltrating lymphocytes and sorted OT-I T cells." (PMID 39925817, 2025).
tumor (continued). "The other four (EPAS1, MXI1, ARNT2, and E2F1) relate to the signaling pathways involved in the processes of tumor formation and development." (PMID 40724805, 2025). "Crispr-mediated ablation of Epas1 promotes terminal exhaustion of young CD8 T cells in tumors, diminishing their anti-tumor activity in young mice." (PMID 39925817, 2025). "Vorinostat has been shown to restore EPAS1 expression in a genetically engineered mouse model of UPS, which leads to a reduction in tumor growth." (PMID 41319167, 2025). "Amplification or epigenetic modification of TERT (rs7734992, 5p15.33) plays a crucial role in ccRCC by maintaining cellular immortality, with HIF1A and EPAS1 regulating TERT expression, enhancing tumour survival under hypoxic conditions." (PMID 41326661, 2025). "Under hypoxia, EPAS1 can promote the production of angiogenesis factors such as VEGF factor to promote tumour angiogenesis and enhance the malignant behaviour of tumour cells." (PMID 38722283, 2024). "In this study, we found one important target, EPAS1/HIF-2α, which is an important hub protein in tumor development and still has research value for anti-tumor targeted therapies." (PMID 38612943, 2024). "EPAS1 becomes ubiquitous in the human body during hypoxia and can promote the production of angiogenesis factors such as VEGF to promote tumour neovascularization, enhance the malignant behaviour of tumour cells and resist radiotherapy." (PMID 38722283, 2024). "We analyzed the expression of genes in tumor and normal samples, and the results showed that NDUFS1, NDUFS2, NDUFC1, and EPAS1 were downregulated in CRC, and SLC7A11, OXSM, LRPPRC, NDIFA11, NUBPL, and CONT1 were upregulated in CRC." (PMID 37978247, 2023). "TF factor motif analysis within H3K27ac peaks revealed 29 MG63-specific TF binding sites, including those for EOMES, PRDM1, EPAS1 (HIF2A), E2F6, and MYC/MAX, which reflect known early development, tumor-initiation, and stemness factors (Worksheet 1)." (PMID 37228489, 2023). "EPAS1 shares 48% identity with HIF-1α whose regulatory functions in glucose metabolism, cell proliferation, angiogenesis, tumor invasion, and survival have been elucidated over the past decades." (PMID 37124944, 2023). "ACSL3, EPAS1, FASN, GSTP1, LDHB, and NEDD4L were identified as the candidate genes through the intersection of tumor-related genes, DEGs, and ferroptosis-related genes." (PMID 35223835, 2022). "To further elicit better predictors amongst the range of PD-L1 expression in tumor tissues, we grouped the samples based on three genetic backgrounds: sporadic cases, pseudohypoxia cluster (SDHB, VHL, EGLN1, EPAS1) and kinase signaling cluster (RET, NF1)." (PMID 36439433, 2022). "Linc01436 worked as a miR-30a-3p sponge to increase the expression of EPAS1 in NSCLC, resulting in promotion of cell growth, invasion and migration in vitro and enhancement of tumor growth and tumor metastasis in mice." (PMID 35928868, 2022). "Our results indicate that EPAS1 has important roles in the pathogenesis of CRC via modulating cellular proliferation, invasion and migration, by acting as a tumour promoter gene." (PMID 34250767, 2021). "These EPAS1 aberrations in CRC were correlated with clinicopathological parameters, including tumour size, histological grade, T‐stages, cancer perforation as well as the presence of synchronous cancer." (PMID 34250767, 2021). "In 88 paired samples, LRRK2, PECAM1, EPAS1, and LDB2 showed significant low expression in tumor samples, which was consistent with previous results." (PMID 32196072, 2020). "The correlation of EPAS1 DNA number amplification and increased mRNA expression in ESCC in the present study indicated that hypoxic tumor niche induces alterations of EPAS1, which in turn can promote carcinogenesis." (PMID 33042797, 2020).
tumor (continued). "Higher frequency of patients with ESCC having tumor stage I and IV showed EPAS1 DNA amplification, whereas the majority of the patients with ESCC having tumor stages II and III showed EPAS1 DNA deletion (p = 0.02)." (PMID 33042797, 2020). "While an increased HIF-1α expression was observed in both tumor-derived GSCs and neural progenitor cells derived from normal brains, the former also show increased levels of HIF-2α (EPAS1)." (PMID 32823815, 2020). "HIF-2α, also known as EPAS1 (Homo sapiens endothelial PAS domain protein 1), influences some biological functions, such as angiogenesis, energy metabolism, cell migration, and tumour invasion." (PMID 31796646, 2019). "Tumor cells adapt to the hypoxic environment partly through stabilization of hypoxia inducible factors HIF1A and EPAS1 (HIF2A), enhancing glycolytic activity to maintain ATP levels when mitochondrial activity has slowed down." (PMID 28804704, 2017). "We suspected that KP tumour cells developed resistance to SAHA, and its effect on Epas1 re-expression, over the extended course of the experiment (8 days)." (PMID 26837714, 2016). "EPAS1, also known as HIF-2α, is a transcription factor that is directly involved in various tumor types." (PMID 26587830, 2015). "The study showed that EPAS-1 plays an indispensible role in SP-1 transcription factor-mediated FBI-1 induction, and participated in tumor cell survival and proliferation." (PMID 25192290, 2014). "In total, 3.5% of the transcriptome is regulated by PARP-1 with 60–70% positively regulated, including genes involved in tumor promotion such as JUND, MDM2, HGF, FLT1 (VEGFR1), EGFR, HIF2A (EPAS1), SPP1 (OPN), MMP28, ANGPT2, and PDGF." (PMID 24350055, 2013). "Consistent with tumor data, we determined that the subgroup 7 cell line (AU565) has significantly higher mRNA levels of HIF1A (HIF-1α) and EPAS1 (HIF-2α) when compared to the subgroup 10 cell line HCC202." (PMID 21672245, 2011). "Over the past years, the proteins HIF1A, EPAS1, and VEGFA have been shown to be eligible targets for anti-tumor therapies." (PMID 39888575, 2026). "For example, our in vitro analysis revealed that aging, but not Epas1 deficiency, impairs CD8 TCR-T cell capability to exhibit a central memory phenotype, which is associated with high anti-tumor activity." (PMID 39925817, 2025). "Thus, Epas1 appears to control expression of several genes involved in infiltration of tumors, proliferation, and survival of CD8 T cells in anti-tumor responses." (PMID 39925817, 2025). "However, CD40, glypican 3 (GPC3), Iroquois homeobox 2 (IRX2), FOXO1, EPAS1, and cyclin-dependent kinase inhibitor 1C (CDKN1C) were consistently down-regulated in tumor tissues and GbPDTOs compared to those in normal tissues." (PMID 41376821, 2025). "At the same time, Vegf expression increased only in the tumor tissue of the SH animals relative to the control, and no changes in Hif1a, Epas1, or Hif3a expression were noted either in the tumor tissues or in the peritumoral area." (PMID 39063041, 2024). "Based on the differential typing of the TME, we identified tumor cell-specific regulatory programs that are mediated by three key transcription factors (TFs), whilst the TF EPAS1/HIF-2α was identified via drug virtual screening through our analysis of ccRCC’s protein structure." (PMID 38612943, 2024). "This is associated with bi-allelic inactivation of the von Hippel Lindau (VHL) tumour suppressor, which forms part of an E3 ubiquitin ligase complex that targets HIF-α subunits (HIF-1α and HIF-2α; also known as EPAS-1) for proteasomal degradation in the presence of oxygen." (PMID 36725335, 2023).
tumor (continued). "Although both HIF1A and EPAS1 genes were upregulated in MES1-like and MES2-like tumor cells, only EPAS1 regulon (not HIF1A regulon) was activated in both MES1-like and MES2-like cells among the top activated regulons." (PMID 35669791, 2022). "By constructing the regulon networks in TAMs, we found that hypoxia-related regulons, EPAS1 and HIF1A, were both activated in the TAM-1 cluster, which differs from the hypoxia response in MES1-like and MES2-like tumor cells." (PMID 35669791, 2022). "Importantly, a pan-cancer analysis of EPAS1 expression levels revealed that PPGL, together with ccRCC, are the human neoplasias with the highest mRNA levels of this gene." (PMID 35740651, 2022). "This “oxygenation heterogeneity” was later confirmed by studies using chemical oxygen probes and the detection of transcripts or proteins induced by hypoxia at the particular tumour areas (e.g., CA9, VEGF, ANGPT2, EPAS1), with the rest of the tumour being relatively well-oxygenated." (PMID 36230775, 2022). "Also, SIPA1 knockdown decreased the expressions of EPAS1, glycolysis-related products and PDK1 in tumor tissues at mRNA and protein levels." (PMID 35096814, 2021). "Most of the tumour samples with no changes or deletion of EPAS1 DNA copy number exhibited similar results in mRNA expressions." (PMID 33114456, 2020). "Surprisingly, Epas1 mRNA levels were only slightly elevated in the SAHA-treated tumours compared with controls, although there was no change in Hif1a levels, as expected." (PMID 26837714, 2016). "Adaptation of tumor cells to growth under hypoxic conditions has been primarily attributed to the accumulation of the hypoxia-inducible transcription factors HIF-1α (expressed by the HIF1A gene) and HIF-2α (expressed by the EPAS1 gene)." (PMID 26057707, 2015). "Our results also suggest that defective anti-tumor activity of aged TCR-T cells may not be solely on decreased Epas1 expression." (PMID 39925817, 2025). "The expression of many classifier genes of the pseudohypoxic cluster (i.e., Epas1, Slc18A1/2, Ndufa4l2, Vegfa) increased with the size of the rat tumors suggesting that they play an important role in tumor progression, but not necessarily in tumor initiation." (PMID 33401758, 2021). "In addition, 61% (n = 22/36) of non-metastasizing tumours had high EPAS1 mRNA overexpression, whereas 78% (n = 7/9) of metastasizing malignant tumours had low EPAS1 mRNA expression (p = 0.057)." (PMID 33114456, 2020). "We speculate that the inhibitory effects of silencing EPAS1 without ADR treatment on tumor growth may be related to the function of BCRP." (PMID 30536571, 2019). "To confirm these findings, we examined expression of EPAS1, which was not available for FGFR3-TACC3-positive patients and is highly enriched in endothelial cells of the tumour vasculature." (PMID 39724753, 2024). "Additionally, because there are limited GWAS data available on patients who also have tumor molecular data, we did not validate the observed associations between the 8q24 germline variant and VHL tumor mutation nor the association between the EPAS1 germline variant and SETD2 tumor mutation." (PMID 33121461, 2020).